TNF (tumor necrosis factor)
Diseases named in the same sentence as TNF in open-access papers (continued):
Sharing a sentence is not in itself a finding about the gene and the disease.
edema (continued). "We observed neutrophil recruitment and pulmonary edema at the earliest on Day 1 following bleomycin treatment suggesting it may result from the early increase of TNF‐α and IL‐1β." (PMID 36898724, 2023). "Furthermore, in a small study with 17 patients, in which TNF was used for isolated limb perfusion, three patients developed respiratory failure secondary to lung edema, but it has to be considered that this trial was performed in cancer patients." (PMID 32410851, 2020). "TNF alpha is the key mediator of pulmonary edema in COVID 19 lung disease." (PMID 32922301, 2020). "In the study, it was found that after DCXC treatment with 10, 30 and 60 mg/kg, inflammatory cell exudation and pulmonary edema were alleviated to a certain extent, and the levels of TNF-α, IL-6 and IL-1β in BALF were also reduced to a certain extent in a dose-dependent manner." (PMID 31186277, 2019). "TNF-α may be involved in the development of brain edema in ALF by affecting brain ammonia through the modulation of Rhcg expression in the brain." (PMID 30134917, 2018). "Our experimental results showed that MP could inhibit carrageenan-induced abdominal edema and downregulate MPO, TNF-α, and iNOS at the protein level, which is similar to the effect of MP in carrageenan-induced paw edema in rodents." (PMID 25141004, 2014). "Therefore, identification of the inflammatory signaling initiated by TNF-α in BMECs is paramount to understanding the mechanisms of infectious brain edema." (PMID 21473788, 2011). "Therefore, PVAC may reduce HCl-induced vascular leakage and neutrophil infiltration by inhibiting IL-6 and TNF-α signaling axis, thereby improving pulmonary edema and lung pathological damage." (PMID 39650159, 2024). "Therefore, the mechanism of anti-inflammatory activity of FECA might act through the inhibitions of the COX-2 and TNF-α level in the model of λ-carrageenan-induced paw edema of mice." (PMID 23887648, 2013). "Anti-inflammatory activity was evaluated in vitro using tumor necrosis factor-alpha (TNF-α)-induced interleukin-1 beta (IL-1β) production in human keratinocyte (HaCaT) cells, and in vivo using a carrageenan-induced rat paw edema model." (PMID 41304926, 2025). "TNF is a key inflammatory initiator in ALI, rapidly amplifying inflammatory cascades, damaging the alveolar-capillary barrier, and promoting pulmonary edema and respiratory impairment." (PMID 41441024, 2025). "Methotrexate administration resulted in increased levels of TNF-α, MPO, GATA3, caspase-3, and pulmonary edema indices, while reducing the levels of TAC, SOD, Gpx, IL-10, T-bet, and FOXP3." (PMID 38245672, 2024). "Reduced levels of COX-2, NO, TNF-α, and IL1-β in tissues obtained from λ-carrageenan-induced paw oedema mice." (PMID 35744969, 2022). "Our findings demonstrate that transferred TNF-EMP can induce histopathological signs that are compatible with endothelial leakage leading to cerebral and pulmonary oedema and haemorrhage in healthy mice." (PMID 24651155, 2014). "Our results show that pulmonary artery perfusion with TNF-α Ab in hypothermic LPD significantly reduces CPB-induced apoptosis and prevents pulmonary edema." (PMID 24386164, 2013). "In the intracranial hemorrhage (ICH) model, CBL can ameliorate secondary injury and promote behavioral performance during the acute phase by reducing brain edema, the inflammatory response, and BBB permeability by decreasing the expression levels of IL-1β, TNF-a, IL-6, and AQP4." (PMID 36074398, 2022). "Our results suggest a reduced expression of pro-inflammatory cytokines including TNF-α, IL-6, IL-1β, and MMP-13 in the ASPP 092 treated ear of the mice in a dose-dependent manner when compared to that of the EPP-induced ear edema mice those are untreated." (PMID 34588910, 2021). "This suggests that inhibition or suppression of microglial activation and release of TNF-α and IL-1β might ameliorate BBB disruption and cerebral edema." (PMID 24916922, 2014).
edema (continued). "In vivo, pulmonary inflammation, pulmonary edema, ultrastructure changes of type II alveolar epithelial cells, MPO activity, total cells, neutrophils, macrophages, TNF-α, IL-6 and IL-1β in BALF, along with the expression of VCAM-1 and VEGF were dose-dependently attenuated by andrographolide." (PMID 23437127, 2013). "displayed significantly antiinflammatory activities in the model of carrageenan-induced paw edema of mice, via inhibiting vascular permeability, which might be related to the reduction of COX-2 and TNF-α." (PMID 21915187, 2012). "A substantial increase in apoptosis or apoptotic biomarkers (e.g. TNF, FAS, Bax, Bad, FAS/FASL and caspases-3/8) was commonly observed in leukocytes, alveolar cells and endothelial cells of lung tissue from severe P. falciparum malaria patients with pulmonary edema and experimental MA-ALI mice." (PMID 38303078, 2024). "The pathogenesis of ARDS is complex, involving different immune cells from innate and acquired immune systems to produce different inflammatory immune cytokines such as tumor necrosis factor-alpha (TNF-α) and ultimately leading to noncardiogenic pulmonary edema." (PMID 34054551, 2021). "Meanwhile, the increase in TNF-α and IL-6 levels in serum and BALF, as well as the marked increase in W/D weight and total BALF protein content induced by hypoxia were indicative of the occurrence of pulmonary edema and increased pulmonary vascular permeability." (PMID 32112644, 2020). "However, non-cardiogenic pulmonary edema, including ARDS, is driven by inflammation-induced lung barrier damage, with pro-inflammatory cytokines (e.g., tumor necrosis factor-α [TNF-α], IL-1β, and IL-6) playing critical roles in propagating inflammation and exacerbating lung injury." (PMID 39479463, 2024).
hypertriglyceridemia (71 papers, 1995 to 2025). A laboratory test result indicating elevated triglyceride concentration in the blood. "Hypertriglyceridemia has been reported as a common lipid abnormality in CF, possibly related to the high fat diet, as well as to elevated circulating TNF-α causing hepatic lipogenesis." (PMID 40248170, 2025). "Elevated levels of interleukin 1 and 6 and tumor necrosis factor α cause fever and hypertriglyceridemia by inhibiting lipoprotein lipase, and the secretion of activated macrophages causes high ferritin levels." (PMID 39055122, 2024). "Hypertriglyceridemia (associated with lipoprotein lipase inhibition caused by excess tumor necrosis factor-alpha [TNF-α]) is found in ~ 36–71% of adults with HLH." (PMID 32664932, 2020). "Like TNF-α, IL-6 is also associated with hypertriglyceridemia." (PMID 24733068, 2014). "The hypertriglyceridemia observed in this model may result from increased release of FFA from adipocytes following activation of the lipase hormone sensitive enzyme by TNF-α associated with lower oxidation of FFA in adipose tissue and less use of glucose in the liver and skeletal muscle." (PMID 28265495, 2017). "Among these, the prolonged elevation of the pro-inflammatory cytokine TNF-α is recognized to lead to inflammatory demyelinating neuropathy and hypertriglyceridemia, aligning with the principal clinical symptoms observed in this patient." (PMID 41561973, 2025). "Simultaneously, IFN-γ and TNF-α (tumor necrosis factor alpha) inhibit lipoprotein lipase, contributing to hypertriglyceridemia." (PMID 41148945, 2025). "TNF also affects the lipid metabolism and hypertriglyceridemia by decreasing lipoprotein lipase activity in adipocytes." (PMID 38396488, 2024). "Already in the 1990s, two studies observed induction of hypertriglyceridemia upon LPS, TNF, or IL-1β exposure in rodents." (PMID 36672634, 2023). "The pro-inflammatory molecules can affect the host metabolic process, as TNF-α was reported to decrease the insulin sensitivity and increase lipolysis in adipocytes, as well as IL-6 was found to contribute to hypertriglyceridemia." (PMID 32256675, 2020). "It was found that TNF-α can suppress lipoprotein lipase synthesis, contributing to hypertriglyceridemia due to decrease of peripheral clearance rate of triglyceride." (PMID 31178854, 2019). "In spite of its role in inflammation, TNF-α increases lipogenesis and lipolysis, thus contributing to lipid abnormalities such as hypertriglyceridemia." (PMID 31569751, 2019). "During acute infections, hypertriglyceridemia can occur due to tumor necrosis factor α (TNF-α) effects on hepatic lipogenesis and lipoprotein lipase." (PMID 30069429, 2018). "High amounts of TNF-α have been reported to concur with increased adiposity, hypertriglyceridemia, and impaired insulin sensitivity in adipose and hepatic tissue." (PMID 29675435, 2018). "Subjects with hypertriglyceridemia have a higher production capacity of IL-6 as well as TNF-α, and increased levels of serum triglycerides are associated with increased levels of IL-6." (PMID 24733068, 2014). "TNF-α was originally identified as a factor that induces hypertriglyceridemia in bacteria infected-animals." (PMID 24733068, 2014). "TNF-α produces hypertriglyceridemia mediated by decreased lipolysis, and increased very density lipoproteins (VLDL) secretion." (PMID 18852869, 2008). "Hypertriglyceridemia promotes a state of low-grade systemic inflammation, characterized by an increase in proinflammatory cytokines, such as interleukin-6 (IL-6), tumor necrosis factor-alpha (TNF-α), and C-reactive protein (CRP)." (PMID 41149060, 2025). "They reported a hypertriglyceridemia in Holstein heifers after an injection of recombinant bovine TNF-α which was accompanied by a temporarily rise of very-low-density lipoprotein concentration and therefore a higher transport capacity from liver into blood circulation and peripheral tissues." (PMID 33435209, 2021).
hypertriglyceridemia (continued). "The first mechanism by which TNF-α increases TG’s plasma concentration is the inhibition of LPL activity, leading to a decrease clearance of TG-rich lipoproteins like very-low-density lipoprotein (VLDL), and thereby causing hypertriglyceridemia." (PMID 34300308, 2021). "TNF-α has been initially recognized to induce hypertriglyceridemia." (PMID 33671547, 2021). "Hypertriglyceridemia and upregulated serum TG subjects produce high levels of IL-6 and TNF-α." (PMID 33671547, 2021). "TNF alpha and IL-6 also suppress lipoprotein lipase synthesis in adipose tissue, which may contribute to hypertriglyceridemia and the low HDL-cholesterol concentrations observed in individuals with intra-abdominal obesity." (PMID 23526980, 2013). "It has been demonstrated that pro-inflammatory cytokines (e.g., TNF-α) induce hypertriglyceridemia." (PMID 23222963, 2012). "Hypertriglyceridemia may result from excess glucose consumption, and it has been reported that the rate of TG and fatty acid clearance is suppressed by cytokines, notably TNF-α, IL-6, and IL-1β, increasing this condition, as our data show." (PMID 39452936, 2024). "Taken together, we conclude that the atheroprotective effect of Maxadilan is mainly downstream of cholesterol-induced inflammation, such as induction of TNF-α and IL-1β and, in addition, may involve activation of vasoprotective signaling, reduction of apoptosis, and hypertriglyceridemia." (PMID 39769009, 2024). "In addition, TNF-α can reduce the activity of lipoprotein lipase and IL-6 increase the uptake of fatty acids to adipose tissue and to the liver, which in turn promotes hypertriglyceridemia." (PMID 32187268, 2020). "Second, hypertriglyceridemia induces the release of more inflammatory cytokines such as interleukin 6 and tumor necrosis factor alpha and reduces the release of anti-inflammatory cytokines such as interleukin 10, which may create a cellular environment conducive to neoplasia." (PMID 32967679, 2020). "Therefore, it is tempting to speculate that the observed hypertriglyceridemia in the blood in LPS-treated seabream may be the result of increased TNFα-induced lipolysis." (PMID 28946685, 2017). "Hypertriglyceridemia in HLH is thought to be secondary to decreased lipoprotein lipase activity, which was initiated by increased TNF-α levels." (PMID 35410268, 2022). "IL-6, IL-1, and TNF-α are responsible for fever, whereas interferon-γ and TNF-α contribute to hypertriglyceridemia by inhibiting lipoprotein lipase and stimulating triglyceride synthesis." (PMID 35244052, 2022). "The anti-TNF treatment neither affected tumour growth nor prevented the serum cholesterol changes, while attenuating the hypertriglyceridaemia and the elevated serum free fatty acid levels." (PMID 7577459, 1995).
hyperuricemia (71 papers, 2012 to 2026). An abnormally high level of uric acid. "Hyperuricemia has been associated with increased levels of pro-inflammatory cytokines, such as interleukin-6 (IL-6) and tumor necrosis factor-alpha (TNF-α)." (PMID 39070258, 2024). "Subsequently, it promoted the expressions of inflammation factors IL-1β and TNF-α, causing immune dysfunction and leaky gut syndrome, followed by exaggerated immune response and intestinal barrier dysfunction, which triggered hyperuricemia progression." (PMID 36432519, 2022). "This ecosystem shift, involving the expansion of opportunistic pathogens like Ruminiclostridium_5, Intestinimonas, and Bilophila, could further facilitate the elevated serum LPS and TNF-α levels observed in hyperuricemia, in turn fueling metabolic inflammation and associated disturbances." (PMID 38088975, 2023). "In addition, many studies reported that hyperuricemia was associated positively with TNF-α, IL-6 and CRP, which suggested that uric acid may have a role in inflammation and subsequent inflammatory related diseases." (PMID 29498657, 2018). "Sedentary behavior increases hyperuricemia risk by elevating proinflammatory cytokines (IL-6, CRP, TNF-α) and reducing anti-inflammatory markers (IL-RA)." (PMID 41404102, 2025). "Hyperuricemia triggers systemic inflammation through ROS-mediated NF-κB activation and peroxidase inhibition, elevating TNF-α, IL-6, and IL-1β." (PMID 40870677, 2025). "For instance, probiotic treatment of hyperuricemia mice using Clostridium butyricum not only lowered blood UA levels but also led to the release of intestinal lipopolysaccharides, tumor necrosis factor-α (TNF-α), and inflammatory factors such as interleukin-6." (PMID 38540830, 2024). "Another study in an experimental model of kidney damage induced by hyperuricemia reported that naringenin reduced hyperuricemia, TNF-α, NF-κB, Cit C, and 8-OHdG, but increased glutathione peroxidase." (PMID 38907737, 2024). "Consistently with previous study, combined with the elevated of Ruminiclostridium_5 and Intestinimonas, we found serum LPS and TNF-a was also elevated in hyperuricemia mice." (PMID 38088975, 2023). "NAY significantly reduced the level of UA in hyperuricemia mice and cells by inhibiting xanthine oxidase activity and reduced the levels of TNF-α, IL-6, and other inflammatory factors in serum and kidney of mice." (PMID 36120294, 2022). "All dose groups of NAY can significantly reduce the level of renal TNF-α in hyperuricemia mice (p < 0.001)." (PMID 36120294, 2022). "Compared with hyperuricemia mice, serum TNF-α levels were significantly reduced in the high dose group (p < 0.01)." (PMID 36120294, 2022). "Berberrubine has been shown to significantly reduce serum urate levels and the levels of inflammatory mediators (IL-1β, IL-6, and TNF-α) in mice with PO- and hypoxanthine-induced hyperuricemia." (PMID 36483739, 2022). "Some animal studies have reported that hyperuricemia can reduce insulin sensitivity by increasing reactive oxidative stress and inflammatory cytokines such as TNF-alpha." (PMID 35740443, 2022). "In a hyperuricemia animal model, uric acid can upregulate the expression of inflammatory factors such as cyclooxygenase-2 (COX-2), IL-1β, and TNF-α and play an important role in the development of complications related to hyperuricemia." (PMID 33897800, 2021). "Clinical trials have shown that serum levels of IL-6 and TNF-α are significantly higher in hyperuricemia patients than in healthy people, and that of IL-6 and TNF-α are significantly increased as sUA levels increase." (PMID 33568990, 2020). "Hyperuricemia induced a state of inflammation and significantly increased IL-1β and TNF-α levels (P < 0.05), while decreasing serum levels of IL-10." (PMID 32528050, 2020). "Recently a study also observed elevated lipopolysaccharide and tumor necrosis factor-α in hyperuricemia mice, suggesting hyperuricemia mice were in low systemic inflammation." (PMID 32742469, 2020).